INS (insulin)
Diseases named in the same sentence as INS in open-access papers (continued):
Sharing a sentence is not in itself a finding about the gene and the disease.
Hypertension (continued). "Both maternal and paternal diet high in fat and sugar seem to lead to impaired glucose and insulin metabolism, higher risk developing T2DM, adiposity, hypertension and hepatic disease in the offspring’s later life." (PMID 33382823, 2020). "The results revealed that insulin use (OR = 0.463, p = 0.046), hypertension (OR = 5.266, p = 0.000), HbA1c (OR = 1.298, p = 0.003), and plasma sLRP1 levels (OR = 0.971, p = 0.005) were associated with MCI in patients with T2MD." (PMID 33013281, 2020). "At lower altitude (<3,500 m), age, hypertension, residence, and TG levels were risk factors for FPG levels; age and TG levels were risk factors for PPG levels; and residence was a risk factor for INS levels." (PMID 33014972, 2020). "Studies in adult rats have shown favorable outcomes of caffeine administration in connection with insulin sensitivity, blood glucose, and hypertension." (PMID 32206470, 2020). "After controlling biomarkers, eGFR, and total cholesterol, only uric acid and insulin independently predicted incident hypertension." (PMID 33346219, 2020). "Potassium plays a critical role in insulin secretion, hypertension and carbohydrate metabolism, and can affect carbohydrate accumulation and glucose homeostasis." (PMID 32377370, 2020). "Several studies reported that high SUA levels induced endothelial dysfunction through vascular resistance in insulin-induced NO production, potentially leading to hypertension." (PMID 32293295, 2020). "Twenty-nine metabolites, involved in phospholipidic and cardiac remodeling, arginine/nitric oxide pathway and antihypertensive and insulin resistance mechanisms, discriminated the metabolic sexual dimorphism of hypertension." (PMID 32371946, 2020). "Among the top-10 variables across all methods were sweet flavor, urine glucose, age, heart rate, creatinine, waist circumference, uric acid, pulse pressure, insulin, and hypertension." (PMID 32157171, 2020). "Age, family history, anthropometry, duration of symptoms, clinical presentation, blood glucose at admission, A1C, lipid profile, arterial hypertension, total diary insulin dose (TDID), microvascular and macrovascular complications were evaluated." (PMID 32647539, 2020). "To find effect modification, we tested for interaction by gender, age, BMI, eGFR, UAE, glucose, insulin, and hypertension." (PMID 32957570, 2020). "We found significant effect modification for age, BMI, eGFR, UAE, glucose, insulin, and hypertension if the product term was added to the crude and adjusted for age and sex Cox regression models." (PMID 32957570, 2020). "Reversion by this same mixture of polyphenols for signs of MS other than hypertension, such as increased visceral adipose tissue, insulin, triglycerides, and HOMA-IR, which were found in this paper, had been previously reported by our group and other authors." (PMID 32210194, 2020). "Age; parity; values of HbA1c, creatinine, TSH, and triglycerides; ARE activity; BDI scores; and rates of insulin use, menopause, nephropathy, and hypertension emerged as significant predictors of diabetic FSD on univariate regression analysis (p ˂ 0.05)." (PMID 32267365, 2020). "On the other hand, the use of insulin, increase in age, experience of blood pressure, and having high blood pressure had significantly decreased the IIEF mean score." (PMID 32874437, 2020). "Thus, a sugar‐rich diet, especially when combined with physical inactivity, may cause overweight and obesity, which, in turn, increases the risk of high blood pressure (e.g. hypertension), dyslipidaemia, peripheral insulin resistance, inflammation, and dental caries." (PMID 32270494, 2020). "High baseline and continuously increasing fasting insulin levels have been reported to be independent determinants for the future development of hypertension in a 4-year follow-up study in healthy adults." (PMID 32235782, 2020).
Hypertension (continued). "All the same, the symptoms are all there: high blood pressure, raised levels of telltale fats called triglycerides found in the blood, and insulin resistance—an acquired resistance to the body's vital glucose-handling hormone." (PMID 31951616, 2020). "This is the first study to have examined the impact of changes in fasting insulin and IR indices over approximately 3 years for incident hypertension in a population-based cohort." (PMID 31728151, 2019). "Studies highlight their effects on improving insulin secretion, enhancing insulin-dependent glucose transport, anti-oxidative, anti-hypertension, anti-mutagenic, anti-genotoxic, anti-allergic, and neuroprotective effects." (PMID 30983995, 2019). "Accordingly, changes in levels of fasting insulin and IR indices showed significant increasing trends for incident hypertension, moving from 1st quartile to 4th quartile." (PMID 31728151, 2019). "On the other hand, humans with an APOC3 mutation benefit from a favorable lipoprotein profile, increased insulin sensitivity, lower incidence of hypertension, and protection against cardiovascular diseases." (PMID 30622162, 2019). "Specifically, compared to reference, the 4th quartile of insulin, HOMA-IR and IGR changes showed significant higher risk for incident hypertension in different models, excluding the 4th quartile of HOMA-IR changes in model 3 [hazard ratio: 1.18 (0.92–1.52)]." (PMID 31728151, 2019). "Calorie intake and physical activity level, major factors in keeping the balance of energy obtained and consumed, can strongly influence hypertension, glucose and lipid metabolism, and insulin sensitivity." (PMID 30972022, 2019). "Allicin enhances insulin activity, and reduces hypertension and hyperlipidemia in diabetic patients." (PMID 31810206, 2019). "The MCI and control group were well matched in age, gender and education levels, as well as the prevalence of smoking, alcohol, hypertension and metformin and insulin usage (all p > 0.050)." (PMID 30837891, 2019). "We found that aging hypertension significantly decreased aortic protein expressions of insulin and IGF-1 receptors, phospho-Akt/Akt, and phospho-eNOS/eNOS, whereas the PCA administration significantly enhanced expression of these proteins in aging SHR." (PMID 30934575, 2019). "Compared with healthy individuals, participants with T1DM were older, had a higher prevalence of arterial hypertension, systolic blood pressure and aPWV values and worse glycemic control and insulin sensitivity." (PMID 31694246, 2019). "Almost one in four participants (23.6%) used insulin and other injectables, 89.3% used oral antidiabetic medicine and 71.2% used oral medicine to treat comorbidities such as hypertension and hyperlipidaemia." (PMID 31805932, 2019). "Data showed no significant statistical difference between the metformin and insulin groups in terms of pregnancy-induced hypertension (RR, 0.56; 95% CI, 0.30 to 1.06; P = 0.08)." (PMID 31781670, 2019). "Changes in fasting insulin levels and IR indices showed significant increasing trends for incident hypertension, moving from 1st to 4th quartiles (all P-values < 0.05)." (PMID 31728151, 2019). "High blood pressure was diagnosed in a large number of control donors and type 2 diabetic donors, especially those receiving insulin treatment." (PMID 31327049, 2019). "Another study demonstrated insulin-specific benefits in adults with essential hypertension and impaired glucose tolerance after 15-day supplementation with 100 g flavan-3-ol-rich dark chocolate." (PMID 31013914, 2019). "Significant differences between males and females were also shown in place of residence (p = 0.022), marital status (p < 0.01), level of education (p < 0.01), employment status (p < 0.01), use of insulin (p = 0.012), and presence of hypertension (p < 0.01)." (PMID 29415696, 2018).
Hypertension (continued). "Associations with metabolic markers were only marginally attenuated, many remaining significant apart from insulin and hypertension, which were borderline significant." (PMID 30124747, 2018). "When we applied Cox's proportional regression analysis, the variables studied in univariate analysis changed significance; thus, in the first model, current age, insulin treatment, arterial hypertension, and HbA1c levels sex were significant." (PMID 29682579, 2018). "Impaired endothelial function precedes the development of prehypertension and hypertension, as seen in hypertensive rats which exhibited reduced vasodilatation to insulin prior to significant hypertension developing." (PMID 29518898, 2018). "The study of STDR and DME also shows that UACR is a more significant risk factor than eGFR, despite eGFR being an important risk factor, with HR having similar values to other variables like arterial hypertension or insulin treatment." (PMID 29682579, 2018). "After adjusting age, gender, BMI, smoking, hypertension and dyslipidaemia, the middle and high insulin level groups still had an OR of 1.51 (P=0.35) and 5.04 (P<0.001) for MetS, respectively." (PMID 29724734, 2018). "Hyperglycaemic women were characterized by visceral obesity, hypertension, higher serum insulin and triglycerides, higher intake of fat and lower consumption of complex carbohydrates and B vitamins." (PMID 29464546, 2018). "The possible explanation is alcohol increases stimulation of sympathetic nervous system, endothelin, insulin resistance and inhibition of vascular relaxing substances which leads to hypertension." (PMID 30526686, 2018). "In a forward regression model, including age, sex, BMI, hypertension, waist-hip ratio, HbA1c, total cholesterol, and fasting glucose/insulin, it was tested which variables were independently related to altered gray matter structure in the whole group." (PMID 29654499, 2018). "The risk for prevalence of MetS in the middle and high insulin group as compared with the low insulin group were assessed by multivariate logistic regression with adjustments for age, gender, smoking, body mass index (BMI), hypertension and hyperlipidaemia." (PMID 29724734, 2018). "There is evidence that around 50% of patients with essential hypertension are also insulin resistant and it is this group which are more likely to develop CVD." (PMID 29518898, 2018). "Of the patients, 67.1% had hypertension, 27.4% had cardiovascular (CV) disease, and 22.8% of the patients were treated with insulin." (PMID 28432319, 2017). "Heritability of fasting glucose and fasting insulin was estimated as 0.52 and 0.47, respectively, in families with hypertension, suggesting that genetic factors are responsible for a large proportion of phenotypic variation in the traits." (PMID 28789618, 2017). "A study revealed increased insulin levels in subjects with hypertension despite normal glucose levels." (PMID 28765644, 2017). "Participants had to be overweight/obese non-insulin–dependent T2D, with controlled hypertension, yet still capable of walking 30 min per day and willing to deal with a time-consuming protocol and inconvenient blood tests and office visits." (PMID 30291068, 2017). "For example, calcium has been linked to weight loss and improvements in lipid profiles and insulin sensitivity; magnesium may be beneficial for blood pressure, insulin sensitivity and lipid profiles; and phosphorus from dairy foods has been linked to reduced risk of hypertension." (PMID 28212320, 2017). "The use of anti-diabetic drugs (e.g., metformin, sulfonylureas and insulin) and anti-hypertension drugs [angiotensin-converting enzyme inhibitors (ACEI) or angiotensin receptor blocker (ARB)] were also not significantly different among the three groups." (PMID 28228847, 2017). "Hypertension was present in 79% and oral hypoglycemic agents and/or insulin were used by > 90% of patients." (PMID 28400202, 2017).
Hypertension (continued). "In our study, insulin level in patients with high blood pressure was lower than that in patients with lower blood pressure." (PMID 28042549, 2017). "Insulin requirements, rates of macrosomia and hypertensive disorders were reduced following nutritional counseling." (PMID 29049303, 2017). "Less than half of all insulin initiators were diagnosed with hypertension (40.6 %; N = 870) and approximately one quarter were diagnosed with nephropathy (26.6 %; N = 571)." (PMID 26759271, 2016). "The risk of CKD was higher in participants who were older or female, had high levels of dioxin, insulin, or uric acid, or had DM, hypertension, or MS (all with p < 0.05)." (PMID 26963719, 2016). "Theprevalence of insulin was similar among men and women (23.8% in women and 22.8% in men),as was the prevalence of hypertension; both sexes presented high rates of hypertension(81.6% in women and 76% in men)." (PMID 27533270, 2016). "There is evidence of a role for the sympathetic nervous system in the relationship between insulin and hypertension in obese patients with hypertension." (PMID 27364051, 2016). "In fact, palm oil used repetitively provokes the oxidation of monounsaturated and polyunsaturated fatty acids, increasing the rate of fats which contribute to cytotoxic fatty acid accumulation resulting in hypertension and the alteration of insulin response." (PMID 26841874, 2016). "In comparison with participants without high dioxin levels, those with high dioxin were older and had higher prevalence of female gender, MS, DM, hypertension, high insulin (≥ 22 mU/L), and high uric acid (> 7 mg/dL)." (PMID 26963719, 2016). "The pathophysiological mechanism linking insulin and hypertension is complex and still needs to be fully elucidated." (PMID 27412111, 2016). "Reduction of plasma insulin levels or creation of insulin sensitization corrects the hypertension induced by fructose." (PMID 27042260, 2016). "One of these cases occurred in a patient with insulin controlled gestational diabetes and hypertension, though the patient was induced and eventually needed emergent cesarean section." (PMID 27610256, 2016). "Insulin signaling via IRS2 continues to stimulate sodium reabsorption in the proximal tubule and causes sodium retention, edema, and hypertension." (PMID 27247938, 2016). "In 1986, Landsberg first described an association of sympathetic outflow and noradrenaline levels, and carbohydrate (but not protein) intake, with subsequent insulin action and thermogenesis, finally resulting in hypertension." (PMID 27147943, 2016). "Multivariate logistic regression analysis indicated that the significant risk factors for DFU were serum CysC, coronary artery disease, hypertension, insulin use, the differences between supine and sitting TcPO2, and hypertension." (PMID 27668262, 2016). "In the final model, a high dioxin level was still associated with CKD (AOR = 1.76, 95% CI: 1.04–2.99), after adjusting for gender, hypertension, insulin level, uric acid level, and age." (PMID 26963719, 2016). "We have used a hypertension rat model to demonstrate that sustained hypertension induces abnormal islet morphology and insulin secretion in response to high glucose and increases oxidative stress in the pancreas." (PMID 27535482, 2016). "These include the duration of DM, insulin treatment, high blood pressure, higher serum lipids, and high glycated hemoglobin urinary albumin excretion." (PMID 27200379, 2016). "This was associated with significant decreases in BMI, waist circumference, HbA1c, triglycerides, HOMA-IR, insulin, glucose levels, and prevalent hypertension." (PMID 26663986, 2015). "AICAR has previously been shown to have a hypotensive effect when given acutely to spontaneously hypertensive rats and humans while chronic AMPK activation lowered blood pressure in insulin resistant rats and in Ang-II-induced hypertension." (PMID 26196300, 2015).
Hypertension (continued). "Previous studies report an association between allele 482Ser and the presence of T2DM in populations from China, Japan, Caucasians, and Korean as well as a link with hypertension in German common people and early insulin secretion in Pima Indians." (PMID 26185753, 2015). "It has also been suggested that insulin acts as a potential mediator of sympathetic overdrive in hypertension and other cardiovascular complications." (PMID 26450431, 2015). "The prognostic factors for CVD in our study were: insulin, older age, male gender, renal failure, hypertension, habit of walking, and being admitted for cardiovascular reasons." (PMID 26056618, 2015). "MS refers to the clinical syndrome gathered by abnormal glucose metabolism, hypertension, and lipid metabolism disorder, which takes the insulin resistance as the basis and central obesity as the main performance." (PMID 26504476, 2015). "The patients with CAD showed a longer history of T2DM and higher BMI and increases in insulin usage, the incidence of hypertension, and the frequency of statin treatment." (PMID 26098780, 2015). "Other factors involved in the developmental programming of hypertension include vascular structural and functional changes, neuroendocrine adaptations to stress, insulin sensitivity, and sympathetic nervous system activity." (PMID 26228391, 2015). "Predictive factors were gender, age, hypertension, renal failure, insulin, admission due to cardiovascular reasons and walking habit." (PMID 26056618, 2015). "Use of insulin can be considered in the treatment of TCTP-induced hyperreactive vascular disease such as hypertension." (PMID 25854427, 2015). "South Asian men were more insulin resistant and more had diagnosed hypertension compared with European men." (PMID 25693751, 2015). "South Asian SABRE participants, who were also younger, were more centrally obese and had higher fasting glucose and insulin levels, but experienced similar triacylglycerol levels and less hypertension than the Framingham random cohort." (PMID 25693751, 2015). "Pregnancy induced hypertension was found significantly less in metformin alone and metformin plus insulin group as compared to insulin alone group (6.2% versus 23.3% versus 36%), P = 0.020." (PMID 25874236, 2015). "In one of these recent large cross-sectional studies, women were less likely to reach the recommended targets despite receiving the same treatment for lipid control and hypertension and they were more likely to be overtreated with insulin." (PMID 25873959, 2015). "Thirty-eight patients (30.6%) used insulin, 10 used pioglitazone (8.1%), 55 (44.4%) had hypertension, and 47 (37.9%) had proteinuria." (PMID 26457195, 2015). "Among these are vascular endothelial dysfunction, disturbed platelet function, decreased fibrinolytic capacity, high levels of advanced glycation end products (AGEs), dyslipidemia, hypertension and reduced insulin sensitivity." (PMID 26382578, 2015). "NF κB is a primary regulator for proinflammatory gene expression and inhibition of the NFκB inflammatory activation has been shown to improve insulin sensitivity and cardiovascular injury in metabolic and hypertensive diseases." (PMID 25928697, 2015). "After adjusting for age, the indicators (central obesity, hypertension, fasting insulin, SHBG, dyslipinaemia) for metabolic disturbances were significantly higher in PCOS than in non-PCOS groups." (PMID 25223276, 2014). "BMI, WC, and WHtR were shown to be the best predictors for biochemical and clinicalparameters and for the diagnosis of high HOMA-IR, glycemia, and fasting insulin levels.WHR was the best predictor for the diagnosis of arterial hypertension." (PMID 25119752, 2014). "The patient's past medical history was significant for diabetes, mild chronic obstructive lung disease, and hypertension for which he is on an insulin regiment and lisinopril for his hypertension." (PMID 25013732, 2014).